PARK7 (Parkinsonism associated deglycase)
Diseases named in the same sentence as PARK7 in open-access papers (continued):
Sharing a sentence is not in itself a finding about the gene and the disease.
Parkinson disease (continued). "DJ-1 (also known as PARK7) has been identified as a causal gene for hereditary recessive Parkinson’s disease (PD)." (PMID 28993701, 2017). "In that regard, Parkinsonism‐associated deglycase (DJ‐1/PARK7) that was detected in all our samples is not only an oxidative stress sensor, but also a chaperone that inhibits protein aggregation, such as α‐synuclein." (PMID 28177569, 2017). "Parkinsonism Associated Deglycase also called DJ-1 plays a protective role against oxidative stress and mutation of Park7 gene causes familial Parkinson’s disease." (PMID 28659758, 2017). "Mutations of the PARK7 gene are associated with Parkinson’s disease 7 (PARK 7, MIM 606324), an autosomal recessive, early-onset form of PD." (PMID 26907355, 2016). "CG1349 (dj-1beta) encodes a Drosophila homolog of the human DJ-1/PARK7 (Parkinson autosomal recessive, early onset 7) gene." (PMID 24393626, 2014). "One of the genes linked with the onset of Parkinson's disease, DJ-1/PARK7, belongs to a novel glyoxalase family and influences mitochondrial activity." (PMID 25063200, 2014). "Mutations in the DJ-1 (PARK7) gene in dopaminergic neurons induce mitochondrial dysfunction and a genetic form of Parkinson's disease." (PMID 24577080, 2014). "This enzyme, DJ-1 (also named PARK7 because it has been associated with early-onset Parkinson’s disease) is GSH-independent and can directly detoxify GO and MGO." (PMID 24324795, 2013). "Remarkably, djr-1.1 and djr-1.2 are homologs of the Parkinson’s disease-associated human gene DJ-1, also known as PARK7." (PMID 24324795, 2013). "Of interest, these differentiating profiles revealed the unique presence of proteins associated with Parkinson's disease namely: aSyn and PARK7." (PMID 21448452, 2011). "Loss of function mutation of Park7/DJ-1 contributed to the pathogenesis of early-onset Parkinsonism." (PMID 21645326, 2011). "For example, our expression screen implicates the gene PARK7, named for causing Parkinson's disease when mutated, as a key player in OxPhos biology." (PMID 19680543, 2009). "DJ-1/PARK7 is the causative gene for hereditary recessive Parkinson’s disease." (PMID 40464736, 2025). "Mutations in the PARK7 (DJ-1) gene are associated with oxidative damage in Parkinson’s Disease." (PMID 39334768, 2024). "Furthermore, DJ-1 encoded for by PARK7 is a cytosolic and nuclear protein implicated in early onset Parkinson's disease." (PMID 37426575, 2023). "Mutations in PARK7 result in an early-onset form of Parkinson’s disease." (PMID 37153596, 2023). "Similarly, an autosomal recessive gene associated with early Parkinsonism, DJ-1 (PARK 7), is dysfunctional in human colonic tissue samples as well as in in vitro and in vivo experimental models of colitis." (PMID 35281490, 2022). "The PARK7 gene encodes this parkinsonism-associated deglycase." (PMID 35203580, 2022). "Mutations in PARK7 may result in the onset and progression of a few neurodegenerative disorders such as Parkinson’s disease." (PMID 35207708, 2022). "Moreover, the secretion of Parkinson's disease- and cancer-associated protein Park7/DJ-1 is mediated by SA." (PMID 32477265, 2020). "In addition, circMap1a also interacts with the mRNAs of Myo6, which is required for BDNF-mediated neurotransmission and Park7, associated to Parkinson’s Disease and encoding a DJ-1 protein protecting brain cells from oxidative stress." (PMID 32849796, 2020). "DJ-1 activity is abrogated by the Park7 (L166P) mutation, associated with primary parkinsonism." (PMID 31054074, 2019). "The Parkinsonism variant PARK7 is caused by mutations in DJ-1, a cysteine pseudoprotease that lacks key residues for catalysis but may regulate the activity of homologous proteases." (PMID 31547314, 2019).
Parkinson disease (continued). "Five to seven pQTL were observed for phosphoglycerate mutase 1 (PGAM1), the putative Parkinson disease autosomal recessive early onset 7 variant 1 (PARK7), triose phosphate isomerase (TPI1), peroxiredoxin 4 (PRDX4), malate dehydrogenase 1 (MDH1) and 3-hydroxyanthranilate 3,4-dioxygenase (HAAO)." (PMID 28424047, 2017). "Here we asked whether the anti-oxidant protein DJ-1 encoded by the Parkinson’s disease gene PARK7 protects islet cells from cytokine- and streptozotocin-mediated cell death." (PMID 26422139, 2015). "Since it is also associated with Parkinson's disease, it will be important to see if there is any mechanistic relationship between neuronal disorders caused by persistent infection with measles virus and its apparent correlation with PARK7 over-expression." (PMID 21533140, 2011). "Mutations in PARK7 can cause autosomal recessive parkinsonism, and the clinical presentation of the early onset and slow progression of this form of parkinsonism is similar to that of the other recessive PD syndromes such as PARK2 (parkin) and PARK6 (PTEN-induced kinase 1, PINK1)." (PMID 22132160, 2011). "We speculated that the fusion of KIAA0319L and PARK7 results in a protein that integrates the endocytosis capabilities of KIAA0319L with PARK7, an enzyme mutated in hereditary Parkinson’s disease, potentially influencing SP-EPN_6 cellular responses to oxidative stress." (PMID 41160379, 2025). "Notably, PARK7, previously linked to oxidative stress in Parkinson’s disease, here correlated strongly with PPD risk, suggesting its role may extend to perinatal mood disorders via exosome-mediated pathways." (PMID 40747300, 2025). "Interestingly, also genes associated with neurodegenerative diseases (NDDs), such as the mRNA encoding for the amyloid precursor protein APP linked to Alzheimer's disease and Parkin-7 (Park7) which is associated with Parkinson's disease (PD) show isoform switching behavior during brain aging." (PMID 38471806, 2024). "The PARK7 rs225119 is located in a gene encoding a redox-sensitive chaperone protein that helps maintain mitochondrial homeostasis and protects neurons from oxidative stress, mutations of which have been found in patients with autosomal recessive early-onset Parkinson’s disease." (PMID 37761946, 2023). "DJ-1 is a protein encoded by the Parkinson disease protein 7 (PARK7) gene that inhibits the aggregation of α-Syn via its chaperone activity, and acidic DJ-1 isoforms are considered biomarker candidates for PD." (PMID 34881082, 2021). "Therefore, it is not surprising to confirm that SUMOylation is implicated in several human disorders such as neurodegenerative diseases associated to huntingtin, ataxin-1, tau, alpha-synuclein, DJ-1 or PARK-7 (Parkinson's disease 7), and superoxide dismutase 1 (SOD-1)." (PMID 22811915, 2012). "For example, CPPs were used to disrupt mutant Huntingtin’s (HTT) protein–protein interactions in a Huntington disease model and DJ-1’s (PARK7) interactions in a Parkinson disease model." (PMID 40014573, 2025). "Interestingly, a decrease in Parkinson Disease (PD)-associated phosphoproteins, such as PARK7 and tau, was observed." (PMID 41422144, 2025). "We investigated the role of DJ-1/PARK7, a Parkinson’s disease-associated gene, in prodromal pain and peripheral neuropathy." (PMID 39486088, 2025). "•High-fat high-sucrose diet exacerbates muscle atrophy in PARK7 KO mice, a model of early-onset parkinsonism." (PMID 40345387, 2025). "A focused subset of Parkinsonism-related proteins—such as DJ-1 (PARK7), succinate dehydrogenase (SDHA), and multiple 26S proteasome subunits—exhibited coordinated dysregulation, as visualized through protein–protein interaction mapping." (PMID 40725009, 2025). "Parkinson disease 7 (PARK7 or DJ-1) is a protein that was shown to have antiapoptotic effects in our previous study." (PMID 40877233, 2025). "A second example, PARK7, named after its role in Parkinson disease, is expressed in almost all human cells." (PMID 40763733, 2025).
Parkinson disease (continued). "•Novel amide-AGEs distinguish patient fibroblasts with PARK7 KO early-onset Parkinson's disease from healthy controls." (PMID 40345387, 2025). "Concurrently, exogenous CX3CL1 improved motor function in Parkinson's disease model mice with the Park7 knockout, promoting survival of tyrosine hydroxylase-positive neurons in the substantia nigra and reducing Iba-1-positive microglial activation." (PMID 40145975, 2025). "A particularly relevant finding in the context of Parkinson’s disease was the significant upregulation of PARK7 (also known as DJ-1) in MPP+-treated zebrafish larvae." (PMID 40725009, 2025). "In 2003, PARK7 was first characterized when a 14 kb homozygous deletion of exons 1–5 was identified in a Dutch family with early-onset parkinsonism." (PMID 38732020, 2024). "Other major potential biomarkers of CSF that have been studied include DJ-1 (Parkinsonism-associated deglycase) and several other variations of tau and neurofilament light chains, which might be useful in a differential diagnosis between various forms of parkinsonism." (PMID 38500934, 2024). "Mutations in SNCA, LRRK2 and VPS35 genes were associated with autosomal dominant PD, while mutations in PINK1, PARK7/DJ-1, PARK2/PARKIN, PLA2G6, ATP13A2, and FBXO7 cause autosomal recessive PD and/or parkinsonism." (PMID 38931832, 2024). "Another important ALS-related gene identified by our analyses, as reported by DisGeNET or ALSoD, is the Parkinson disease-related PARK7 gene." (PMID 38672428, 2024). "Proteins known to be involved in Alzheimer’s disease progression, (such as CLU, APOE, and ADAM10) and Parkinson’s Disease (such as PARK7 and VPS35) were also identified, suggesting a potential role of GDE2-released EVs in neurodegeneration." (PMID 39272985, 2024). "A novel oncogene originally identified in Parkinson's disease named Park7 or Dj‐1 is reported to be relative to autosomal‐recessive hereditary Parkinson's disease." (PMID 39238115, 2024). "In the NHP CSF, 983 proteins were identified by at least two unique peptides, including proteins with key roles in neurological diseases, such as APP, TREM2 and ApoE in AD, DJ-1/PARK7 in Parkinson’s disease and the prion protein in prion diseases." (PMID 36810097, 2023). "Another commonly used name for DJ-1, PARK7, reveals its indispensable function in neurodegenerative diseases, i.e., Parkinson’s disease." (PMID 37108572, 2023). "We also find that propachlor in particulartargets Parkinson’s disease-associated proteins GAPDH and PARK7,decreasing their cellular activity." (PMID 37427419, 2023). "The superfamily includes human DJ-1(hDJ-1/PARK7), a well-explored protein that induces a familial form of Parkinson’s disease (PD) through its genetic mutations." (PMID 37548361, 2023). "PARK7 is recognized for its neuroprotective role in Parkinson’s disease and has been reported to significantly regulate cell survival and cancer progression in various cancers." (PMID 38304232, 2023). "The dataset provides a general resource for Parkinson's as it defines expression of other Parkinson's-encoded proteins including SNCA, PARK7/DJ1, VPS35, VPS13C, ATP13A2 and LRRK2 that will be of interest to the Parkinson's field more widely." (PMID 37456110, 2023). "DJ-1 (also called PARK7) is a ubiquitously expressed protein involved in the etiology of Parkinson disease and cancers." (PMID 36671412, 2022). "Apart from Parkinson’s disease, PARK7 has been involved in various complexities such as cancer and infertility." (PMID 35207708, 2022). "Deficiency in a key familial Parkinson’s disease gene, PARK7/DJ‐1, reduces immunoaging in T cell compartments of both human and mice at both cellular phenotypic and functional levels." (PMID 35037711, 2022). "Intriguingly, cluster 7 microglia also showed high expression of genes involved in the pathogenesis of Parkinson’s disease, such as synuclein and protein deglycase DJ-1 (SNCA and PARK7)." (PMID 35149686, 2022).
Parkinson disease (continued). "Mutations in one such gene, DJ-1 (also known as PARK7), associate with an early-onset recessive form of Parkinsonism." (PMID 34697772, 2021). "Protein deglycase DJ‐1 (DJ‐1), a 189‐amino acid protein (also known as PARK7), was first identified as an original oncogene accountable for the autosomal recessive early‐onset form of Parkinson's disease." (PMID 33501750, 2021). "In our previous work, we characterized non-germline ASMs in the mouse genome at two genes, Hcn2 and Park7, with potential in Parkinson’s disease." (PMID 32178731, 2020). "Of potential interest is Park7 RNA (DJ-1), which is extensively investigated as related to early onset Parkinson’s Disease." (PMID 33115496, 2020). "Alpha-synuclein protein, leucine-rich repeat kinase 2 (LRRK2), Parkinson disease protein 7 (PARK7), and DJ-1, as well as myocyte-specific enhancer factor 2D protein (MEF2D), which are dysregulated or mutated in Parkinson’s disease, are CMA substrates." (PMID 32792938, 2020). "For instance, PARK7 (protein/nucleic acid deglycase DJ‐1) and SOD1 (superoxide dismutase 1) are risk genes for Parkinson's disease and amyotrophic lateral sclerosis, respectively." (PMID 32485097, 2020). "Previous study has shown increases in the expression of PARK-7 and HSP70 in transgenic mice to express Parkinson’s disease related to neuroprotection caused by the practice of physical exercise." (PMID 30274397, 2018). "Mutations in seven genes were robustly associated with autosomal dominant (SNCA, LRRK2, EIF4G1, VPS35) or recessive (parkin/PARK2, PINK1, DJ1/PARK7) PD or parkinsonism." (PMID 29881367, 2018). "Other genes that associate with Parkinson’s disease that were also repressed were NUB1 which encodes a Lewy body protein, and DJ-1 (aka PARK7) whose product can bind LRRK2 and is associated with a recessive form of Parkinson’s disease." (PMID 30374342, 2018). "Parkinson disease (autosomal recessive, early onset) 7, encoding PARK7 protein (also called DJ-1), plays important roles in many carcinogenesis processes and is essential in modulating inflammation." (PMID 28036277, 2017). "Mutations in parkinsonism associated deglycase (PARK7) gene, which encodes for the human DJ-1 (hDJ-1)/PARK7 protein, are associated with autosomal recessive early-onset forms of Parkinson’s disease (PD)." (PMID 27556455, 2016). "DJ-1, also known as PARK7, was initially mapped as the third locus for the autosomal recessive, early-onset, inherited form of Parkinson’s disease." (PMID 27763504, 2016). "For examples, NRF1 target genes- PARK2, PARK6 (PINK1), PARK7, PAELR (GPR37) are associated with Parkinson’s disease." (PMID 27983596, 2016). "The protein DJ-1, which is the product of the familiar gene for Parkinson's disease, PARK7, enhances the expression of type I Cu/Zn-SOD in connection with the Erk1/2-Elk1 cascade." (PMID 24672633, 2014). "The third group is composed of proteins involved in oxidative phosphorylation, Alzheimer's and Huntington's diseases (NADH dehydrogenases and PSENEN), antioxidant function and Parkinson's disease (PARK7)." (PMID 24587296, 2014). "Although most of the genes were involved in several of these pathways, some of them were restricted to Huntington’s disease (AP2B1, CREB3L4, POLR2H and SOD1), to Alzheimer ́s disease (NAE1, FAS) or to Parkinson’s disease (PARK7)." (PMID 24742402, 2014). "Previous reports showed that the translated protein of Park7 increased 4 days after ONC in rats and that mutations in Park7 were associated with Parkinson’s disease (PD)." (PMID 25407019, 2014). "Mutations in the DJ-1 gene on 1p36 (PARK7), including exonic deletions and point mutations, have been associated with a monogenic early-onset autosomal recessive form of parkinsonism characterized by slow progression and response to levodopa." (PMID 22623900, 2012). "Although most PD cases are sporadic, mutations in parkin (PARK2), DJ-1 (PARK7) and PINK1 (PARK6) have been linked to recessively inherited forms of parkinsonism." (PMID 22792356, 2012).
Parkinson disease (continued). "For example, this would hold true for Nfe2l2 (Nrf2) and Park7 (Parkinson disease (autosomal recessive, early onset) genes as joint regulators of a common target gene." (PMID 18769717, 2008). "Respective mutations in five genes—SNCA (α-synuclein), PARK2 (parkin), PARK7 (DJ-1), PINK1, and LRRK2—can cause parkinsonism that resembles idiopathic PD." (PMID 18539534, 2008). "To date, associations between three different genes/loci and early-onset Parkinson's disease (EOPD) have been identified: PARK2, which encodes parkin, PARK6, which encodes PINK1, and PARK7, which encodes DJ-1." (PMID 17324265, 2007). "DJ-1 (also known as PARK7) protein acts as a sensor for oxidative stress and antioxidant activity, and mutations in this protein cause an inherited form of Parkinson's disease." (PMID 40827382, 2025). "The effects of the functional congee containing dried tomato powder on the alterations in the neurotransmitters playing pivotal roles in cognitive function such as acetylcholine and monoamine and Parkinson’s biomarkers such as alpha-synuclein and PARK7 were also investigated." (PMID 40724595, 2025). "Interestingly, recent studies have revealed that mitochondrial PARK7 (Parkinson’s disease 7) and LRRK2 (leucine-rich repeat kinase 2) genes are related to an increased risk of IBD." (PMID 39000169, 2024). "A case of parkinsonism-ALS-dementia complex has been found in an Italian family, in which three patients carried homozygous E163K mutations in PARK7 exon 7 and a homozygous g.168_185dup mutation in the PARK7 promoter." (PMID 38672428, 2024). "Variants in seven genes (LRRK2, GBA1, PRKN, SNCA, PINK1, PARK7 and VPS35) have been formally adjudicated as causal contributors to Parkinson’s disease; however, individuals with Parkinson’s disease are often unaware of their genetic status since clinical testing is infrequently offered." (PMID 39074992, 2024). "There is a genetic component to the disease, which accounts for between 10 and 15% of cases, with several individual genes (such as LRRK2, SNCA, PINK1, PARK7 and PRKN) associated with Parkinson’s disease and over 90 gene loci that can increase the risk of developing Parkinson’s disease." (PMID 38276234, 2024). "Parkinson’s disease (PD) is associated with mutations in several proteins that have been linked with proteasomes, including alpha-synuclein (α-SNCA), protein deglycase DJ-1 (PARK7), UCHL1, PTEN-induced kinase 1 (PINK1), and PD protein 2 (PARK2, parkin)." (PMID 38067336, 2023). "Likewise, SNCA (α-synuclein), PARK2 (parkin), PARK7 (DJ-1), PINK1 and LRRK2 are the mutated genes of parkinsonism, among which mutations in both PARK2 (parkin) and LRRK2 are the most common genetic causes." (PMID 36478742, 2022). "Although 6RK73 showed more potent inhibition against UCHL1 and better cellular engagement than LDN-57444, it showed limited cellular selectivity with a range of off-targets, particularly against PARK7, a redox-responsive chaperone protein involved in Parkinson’s disease." (PMID 34497382, 2022). "GLXIII belongs to the DJ-1 protein superfamily, also known as PARK7, and its protein products are well characterized in mammalian tissues because they are linked to the development of Parkinson's disease." (PMID 36242617, 2022). "Of note, the Parkinson’s disease pathway includes dysregulation of caspase 3 and Park7 — two genes which were significantly upregulated following exposure to TBI + DM autoantibodies plus some genes that did not meet all criteria but were identified as statistical hits in the pathway analysis." (PMID 34013450, 2021). "The quantitative analysis by the nano-LC-MS method focused on 95 different Parkinson’s disease-relevant proteins (for example, the myelin basic protein, thiosulfate sulfur transferase, and PARK7); among those, only one, PARK7, presented significantly different levels due to treatment." (PMID 33429934, 2021).